BRAF (B-Raf proto-oncogene, serine/threonine kinase)
Diseases named in the same sentence as BRAF in open-access papers (continued):
Sharing a sentence is not in itself a finding about the gene and the disease.
glioblastoma (continued). "Further supporting the clinical utility of MEK inhibition in glioblastoma are several case reports of successful D + T (dabrafenib + trametinib) therapy among BRAF V600E mutants." (PMID 40725122, 2025). "Targeted therapies for rare actionable alterations (e.g., BRAF mutations and NTRK fusions) need further evidence of clinical benefit in glioblastoma." (PMID 41301694, 2025). "Although less common, the MAPK MEK-ERK1/2 pathway has been implicated in increased cell survival, migration, and invasion in glioblastoma, with direct upstream mutations in the MAPK pathway having been identified, namely in RAS and BRAF." (PMID 40725122, 2025). "All but one tumor with Class III BRAF alterations were glioblastomas, while the remaining one was a grade 3 IDH-mutant astrocytoma." (PMID 36854806, 2023). "The glioblastoma cell line DBTRG-05MG with the BRAFV600E mutation showed high levels of both p-BRAF and KCNMA1 with a correspondingly hyper-activated BRAF/MAPK pathway." (PMID 36763212, 2023). "As the extensive crossover of the MAPK and PI3K/AKT/mTOR signalling cascades have been described thus far, it is no wonder that targeting broad effector molecules such as AKT, mTOR, or BRAF/MEK have proven difficult as a treatment strategy in glioblastoma." (PMID 37857607, 2023). "Our findings suggest that mTOR inhibition by CLD is effective in treating BRAF V600E mutant glioblastomas." (PMID 35159037, 2022). "Pharmacological inhibition of autophagy with CQ also helped overcome resistance to the BRAF inhibitor vemurafenib in glioblastoma cells." (PMID 36294938, 2022). "Immunohistopathological analyses identified the lesion as an isocitrate dehydrogenase (IDH) wild-type epithelioid glioblastoma with O6-methylguanine-DNA methyltransferase (MGMT) methylation at 12% and BRAF V600E mutation." (PMID 35130969, 2022). "Our case describes an atypical primary bilateral manifestation of BRAF V600E-positive epithelioid glioblastoma with rapid metastasis and meningeosis glioblastoma while under adjuvant chemoradiotherapy." (PMID 35130969, 2022). "The integrated genomic and transcriptomic analysis of the tumors showed EGFR, PDGFRA, FGFR3, NF1, and BRAF/RAF1 mutually exclusive alterations within the glioblastoma IDH-wild-type category." (PMID 34572759, 2021). "Anti-VEGFA drugs could benefit proneural glioblastoma (GBM) patients, and anti-PD-1 drugs seem effective for BRAF mutated GBM." (PMID 34079802, 2021). "A recent Phase I/II study of DSF and Cu++ with concurrent radiation therapy and TMZ for newly diagnosed glioblastoma demonstrated promising preliminary efficacy for a subset of tumors with IDH1, BRAF, and NF1 mutations." (PMID 34731160, 2021). "In the present study, we identified novel mutations in a glioblastoma patient and first screened a chemical library of more than 1500 FDA-approved drugs to find established drugs, which target novel BRAF and PIK3R1 mutations." (PMID 33313992, 2021). "Pharmacological and genetic inhibition of the MAPK pathway suppressed c-Myc and LAT1 expression in BRAF V600E-mutated PLNTY and glioblastoma cells." (PMID 32811569, 2020). "Conversely, glioblastoma patients harboring BRAF exon 15 p.V600E have the same prognosis as wild-type patients, despite the prevalence of epithelioid morphology without isocitrate dehydrogenase (IDH) alterations." (PMID 33260892, 2020). "The relationship of anaplastic PXA to epithelioid glioblastomas, which also carry the BRAF V600E alteration, remains unsettled." (PMID 31748891, 2020). "We also found that genetic and/or pharmacological BRAF inhibition suppressed MAPK pathway activation and attenuated LAT1 expression in BRAF V600E-mutated-PLNTY cells and -glioblastoma cell lines." (PMID 32811569, 2020).
glioblastoma (continued). "A few clinical cases of BRAF V600E mutant glioblastomas responding to small molecule inhibitor treatment with vemurafenib and dabrafenib have been published together with encouraging results." (PMID 31181803, 2019). "Previous studies in BRAF wild-type glioblastoma models have already demonstrated a central role of GABPA in activation of the mutant TERT promoter." (PMID 31391125, 2019). "BRAF mutation and IDH1 mutation identify glioblastomas with less aggressive clinical course and H3F3A-K27M mutation defines glioblastomas with dismal prognosis." (PMID 26452024, 2016). "Mutational status of BRAF, H3F3A, HIST1H3B and IDH1 were examined in all 107 young adult glioblastomas." (PMID 26452024, 2016). "In 107 glioblastomas aged from 17 to 35 years, mutually exclusive BRAF-V600E (15%), H3F3A-K27M (15.9%), H3F3A-G34R/V (2.8%) and IDH1-R132H (16.8%) mutations were identified in over half of the cases." (PMID 26452024, 2016). "Comparing PDGFRA expression across BRAF, IDH1 and H3F3A mutated glioblastomas, positive expression co-occurred in 50% (10/10) of H3F3A mutated tumors, 27.8% (5/13) of IDH1 mutated tumors and 12.5% (2/16) of BRAF mutated tumors (p = 0.05)." (PMID 26452024, 2016). "BRAF-V600E identified a clinically favorable subset of glioblastomas with younger age, frequent CDKN2A homozygous deletion, and was more amendable to surgical resection." (PMID 26452024, 2016). "Combining BRAF, H3F3A and IDH1 mutations allowed stratification of young adult glioblastomas into four prognostic subgroups." (PMID 26452024, 2016). "In summary, our study demonstrates recurrent BRAF, IDH1 and H3F3A mutations in young adult glioblastomas with clinical impacts." (PMID 26452024, 2016). "Although those studies were on pediatric glioblastomas, our study provided complementary results to theirs and supported the clinical significance of BRAF-V600E testing in glioblastoma of young person." (PMID 26452024, 2016). "However, the few studies of adult classical glioblastoma (c-GBM) with the BRAF V600E mutation lack detailed characterization of the tumors." (PMID 25885250, 2015). "This is the first report of a complete response of relapsed glioblastoma multiforme to targeted BRAF inhibitor therapy." (PMID 24725538, 2014). "In our analysis we detect BRAF V600E mutations in 12 of 20 (60%) WHO grade II PXA, in 1 of 6 (17%) PXA with anaplasia and in 1 glioblastoma arising in a PXA." (PMID 21479234, 2011). "Importantly, BRAF inhibitors plus temozolomide increased the survival in murine models of human glioblastoma." (PMID 40332381, 2025). "MAPK pathway recovery may act as a secondary mechanism of resistance in glioblastomas harboring BRAF V600E after the treatment with BRAF inhibitors." (PMID 37231247, 2023). "In this paper, we report a case of recurrent glioblastoma (GBM) harboring BRAF V600E alteration who initially responded to BRAF and MEK inhibition and subsequently developed treatment resistance by histological transformation to gliosarcoma and acquired an emerging KRASG12D and NF1L1083R mutations." (PMID 37231247, 2023). "The strong immunostaining of BRAF and PI3KR1 indicated that the primary antibodies used for immunohistochemistry detect not only wildtype but also mutated forms of these proteins and that both proteins were expressed at high levels in this glioblastoma case." (PMID 33313992, 2021). "To confirm the reproducibility of these molecular features, we used patient-derived YMG62 cells (epithelioid glioblastoma with the BRAF V600E mutation), which exhibited high 11C-methionine uptake by PET imaging, and AM-38 glioblastoma cells (BRAF V600E mutant)." (PMID 32811569, 2020). "The similar high frequency of BRAF V600E in epithelioid glioblastomas and PXAs suggests that both tumors may belong to one family with divergent morphologic features." (PMID 31181803, 2019). "BRAF V600E mutations and FGFR fusions are even found in a small minority of glioblastomas." (PMID 27812792, 2017).
glioblastoma (continued). "In our current study focusing on young adult patients aged from 17 to 35 years, 15% of patients had BRAF mutation but no BRAF mutation was identified in seven cases of secondary young adult glioblastomas." (PMID 26452024, 2016). "Our study reveals that BRAF, H3F3A and IDH1 mutations are associated with distinct clinical features and can stratify young adult glioblastomas into prognostic subgroups, which have important clinical implications in refining the prognostic classification of glioblastomas in young adults." (PMID 26452024, 2016). "BRAF V600E mutation has not been previously reported in gcGBM but it has been reported to occur at low frequency in glioblastoma and in one case of gliosarcoma." (PMID 21479234, 2011). "However, 54% to 93% of epithelioid glioblastomas express BRAF V600E." (PMID 37568598, 2023). "Our series of glioblastoma samples represents IDH-wt tumors without BRAF and H3K27 mutations." (PMID 37568598, 2023). "In adults with BRAF-mutated CNS tumors, BRAFV600E is most frequent in glioblastoma (~50%), and is common in epitheloid GBM, followed by LGG (~22%), and PXA (18%)." (PMID 37920169, 2023). "For example, a high HyperZ index was associated with BRAF in COAD and IDH1 in glioblastoma (GBM); both genes are linked to CIMP in cancer." (PMID 29125844, 2017). "Moreover, to our knowledge, there is no detailed report of the BRAF V600E mutation in an adult glioblastoma with classical histologic features (c-GBM)." (PMID 25885250, 2015). "While not a predominant mutation in glioblastoma multiforme, the increased prevalence of BRAF V600 mutations in pediatric CNS tumors and certain subtypes marks a population to whom this therapy could be applied." (PMID 24725538, 2014). "This case supports the use of BRAF and MEK inhibition for the treatment of BRAFV600E glioblastoma in the upfront setting." (PMID 39036436, 2024). "We report a case of recurrent glioblastoma (GBM) harboring BRAF V600E alteration who initially responded to combined BRAF + MEK inhibition and subsequently developed treatment resistance by histological transformation to gliosarcoma and acquisition of oncogenic KRASG12Dand an NF1L1083R mutation." (PMID 37231247, 2023). "GBM-IDH-wt include three variants: giant cell glioblastoma, gliosarcoma, and a novel and provisional variant, the epithelioid GBM characterized by large epithelioid cells and the presence of the BRAF V600E mutation." (PMID 33585240, 2020). "A case report illustrates stable disease for 10 months in a BRAF-mutant epithelioid GBM patient treated with dabrafenib alone; a very recently published report shows dramatic, albeit transient response to dabrafenib and trametinib in two BRAF V600E-mutant epithelioid glioblastomas." (PMID 31345255, 2019). "The observed up-regulation of BRAF expression by NFBTA is thus considered critical since BRAF is known to activate apoptosis stimulated by mitogen-activated protein kinase (MAPK or MAP kinase), and MAPK signaling pathways in glioblastoma cells." (PMID 31261921, 2019). "Among the molecular biomarkers evaluated, BRAF, H3F3A-K27M, IDH1 and PDGFRA demonstrated prognostic relevance in young adult glioblastomas." (PMID 26452024, 2016). "Co-evaluation of BRAF, IDH1 and H3F3A-K27M status stratified young adult glioblastomas into four prognostic groups across the cohort (p < 0.00001)." (PMID 26452024, 2016). "For instance, glioblastomas with EGFR amplification may be sensitive to EGFR inhibitors, and tumors that are BRAF mutant-dependent can be treated with BRAF/MEK inhibitors." (PMID 40806492, 2025). "On the other side, glioblastomas that recur after therapy increased the amount and activation (phosphorylation) of proteins involved in synaptic formation, GTPase activity, and oxidative phosphorylation driven by the activity of RAS, BRAF, and MAPK proteins." (PMID 40332381, 2025).
glioblastoma (continued). "While the BRAF V600E mutation is found in about 60% of pleomorphic xanthoastrocytoma (PXA), 50% of gangliomas, 9% of PA and 2–12% glioblastoma, the KIAA1549–BRAF fusion is frequently found roughly in 50–80% of PA and pilomyxoid astrocytomas (PMA), which is an aggressive variant of PA." (PMID 35363819, 2022). "Finally, we identified novel small molecules that effectively targeted cells carrying mutant BRAF and PIK3R1, implying their potential for personalized glioblastoma therapy." (PMID 33313992, 2021). "Following gross-total resection, the histopathological diagnosis was that of glioblastoma versus anaplastic PXA, and the tumor had high-grade morphological features, a BRAF V600E mutation, and was IDH1 (R132H) negative." (PMID 31806041, 2019). "Even though a clear prognostic difference could not be established yet, BRAF V600E mutant glioblastomas have some distinct histopathological and molecular features." (PMID 31181803, 2019). "Our experiments are focused on glioblastoma–IDH-wild type, and no disease-defining alterations were present in histone, BRAF or other genes." (PMID 34996478, 2022). "Mice with orthotopic xenografts created from injected AM-38, a BRAFV600E glioblastoma cell line, showed reduced intracranial tumor growth when treated with PLX4720, but wild-type BRAF intracranial tumors treated with PLX4720 had no survival advantage or delay in tumor growth." (PMID 26525348, 2015).
anaplastic thyroid cancer (132 papers, 2007 to 2026). "For anaplastic thyroid cancer with BRAF V600E mutation, the combination of dabrafenib plus trametinib (BRAF/MEK inhibitors) is FDA-approved." (PMID 41463055, 2025). "Here, we present the case of a patient diagnosed with BRAF-mutant anaplastic thyroid cancer with an unusual diagnostic course highlighting nuances in molecular testing." (PMID 41562808, 2025). "This case highlights the complexities and potential benefits of targeted therapy in managing BRAF-mutated anaplastic thyroid cancer." (PMID 41562808, 2025). "In both colorectal and anaplastic thyroid cancer, the presence of mutations in the BRAF gene, particularly the V600E mutation, has been shown to significantly worsen prognosis and therapeutic outcomes." (PMID 40004697, 2025). "Our data show that MC4R is present and highly expressed in human colorectal adenocarcinoma (wt Caco-2 and BRAF-mutated HT-29) and in anaplastic thyroid carcinoma cells (BRAF-mutated 8305C)." (PMID 40004697, 2025). "The utilization of dabrafenib and trametinib as therapeutic approaches for anaplastic thyroid carcinoma characterized by the presence of the BRAF V600E mutation represented a novel strategy that exhibited good clinical efficacy and favorable tolerability." (PMID 38420016, 2024). "This phase II trial studies the effect of pembrolizumab, dabrafenib, and trametinib before surgery in treating patients with BRAF V600E-mutated anaplastic thyroid cancer." (PMID 37007127, 2023). "In conclusion, our results suggest that the combinatorial use of BRAFi and diclofenac is likely to represent a new possible therapeutic approach to treat BRAF-mutated papillary and aggressive anaplastic thyroid carcinomas." (PMID 37198319, 2023). "This trial studies how well dabrafenib, trametinib, and intensity modulated radiation therapy (IMRT) work together in treating patients with BRAF mutated anaplastic thyroid cancer." (PMID 37007127, 2023). "The aim of this study was to describe the oncologic outcomes of patients with BRAFV600E-mutated anaplastic thyroid cancer (ATC) who had neoadjuvant BRAF-directed therapy with subsequent surgery." (PMID 36762947, 2023). "Dabrafenib plus trametinib for BRAF mutated anaplastic thyroid cancer provides an effective treatment option for this aggressive cancer with a dismal prognosis." (PMID 37434642, 2023). "Squamous cell carcinoma often harbors BRAF mutations, and this is of particular importance, since patients with BRAF-mutant anaplastic thyroid carcinoma can benefit from treatment with targeted drugs." (PMID 36964880, 2023). "In this study, we demonstrated another important pathway for conferring resistance to cell death in papillary and anaplastic thyroid cancer cells with the BRAF V600E mutation." (PMID 35748101, 2022). "Compared with the negative control group and BRAF WT overexpression, the loss of TMRE was significantly delayed in papillary and anaplastic thyroid cancer cells with BRAF V600E overexpression." (PMID 35748101, 2022). "We used a panel of four human anaplastic thyroid carcinoma (ATC) cell lines harboring BRAF or RAS mutations to analyze ERK dynamics and tumor-specific characteristics." (PMID 36056964, 2022). "The results of flow cytometry‐based measurement of apoptosis and necrosis using Annexin V‐FITC/PI staining further confirmed BRAF V600E‐deficient anaplastic thyroid cancer cells promoted cell death." (PMID 35748101, 2022). "Considering these remarkable results previously untreatable ATC, the FDA approved the combination therapy for treatment of BRAF V600E mutated anaplastic thyroid cancer." (PMID 34335481, 2021).